EN2 (engrailed homeobox 2)
Diseases named in the same sentence as EN2 in open-access papers (continued):
Sharing a sentence is not in itself a finding about the gene and the disease.
prostate carcinoma (continued). "Therefore, from our studies we conclude that En-2 is a candidate oncogene in prostate cancer and its PAX2-regulated expression contributes to prostate cancer cell growth." (PMID 21566742, 2008). "Western blot analysis of EN2 protein expression in the prostate cancer cell lines after 3 days of PAX2 siRNA treatment demonstrated that EN2 expression was decreased 70% in PC3 (lane 2) and 26% in LNCaP (lane 4) prostate cancer cell lines as compared to PC3 (lanes 1) and LNCaP (lanes 3) controls." (PMID 21566742, 2008). "In addition, Engrailed 2 protein (EN2), a transcription factor bearing a homeodomain, is secreted into the urine by prostate cancer cells, distinct from normal prostate tissue and benign prostatic hypertrophic cells that do not exhibit EN2 secretion." (PMID 38250812, 2023).
bladder cancer (9 papers, 2017 to 2025). "EN2 expression and secretion may be an early event in bladder tumorigenesis independent of the specific molecular dysregulation associated with bladder cancer." (PMID 39607581, 2025). "This further supports the diagnostic role of EN2 in bladder cancer." (PMID 37627900, 2023). "Abnormal expression of EN2 has been observed in a variety of human cancers, such as bladder cancer, ovarian cancer, and breast cancer." (PMID 39607581, 2025). "Richard Morgan reported that EN2 is expressed in, and secreted by primary or recurrent bladder cancer." (PMID 39607581, 2025). "EN2 mRNA expression was significantly higher in bladder cancer cells than in the human uroepithelial cells (SV-HUC-1)." (PMID 37627900, 2023). "The upregulation of EN2 and the downregulation of miR-27b were found in bladder cancer tissues and cell lines." (PMID 37627900, 2023). "Majority of bladder cancer cell lines expressed higher EN2 mRNA levels compared with the normal urothelium cell line (NHU-BTERT)." (PMID 37627900, 2023). "EN2 is a direct target of miR-27b in bladder cancer, wherein EN2 is negatively regulated by miR-27b." (PMID 37627900, 2023). "EN2 is overexpressed in a number of different malignancies, most notably prostate and bladder cancer, and urinary EN2 protein has been shown to be a potential diagnostic marker of both of these diseases." (PMID 28423659, 2017). "The overexpression of EN2 reversed the biological effects of miR-27b on bladder cancer cells." (PMID 37627900, 2023). "Taken together, EN2 may be a candidate oncogene that plays a crucial role in the development and progression of bladder cancer." (PMID 37627900, 2023). "In addition, EN2 may be a potential therapeutic target for bladder cancer." (PMID 37627900, 2023). "These bladder cancer cell lines (EJ, RT4, RT112, and UMUC3) had moderate to high EN2 expression, whereas the normal urothelium cell line had low EN2 expression." (PMID 37627900, 2023). "Engrailed-2 (EN2), a member of the HOX gene family, has been found to overexpress in various kinds of cancers like PC, breast cancer and bladder cancer, and play important roles in oncogenesis." (PMID 32539763, 2020). "Therefore, urinary EN2 protein could be used as a sensitive and specific biomarker for NMIBC to reduce the use of cystoscopy for bladder cancer surveillance." (PMID 37627900, 2023).
colorectal cancer (9 papers, 2020 to 2025). A primary or metastatic malignant neoplasm that affects the colon or rectum. "The APC tumor suppressor, frequently mutated in colorectal cancer, was also found to interact only with EN2." (PMID 37686522, 2023). "For example, circ_0000467 was reported to regulate colorectal cancer development via miR-382-5p/EN2 axis." (PMID 34288804, 2021). "The expression of EN2 was examined by qRT-PCR and Western blot in the colorectal cancer tissues and adjacent normal tissues, together with the CRC cell lines (HCT8, SW620, and SW480) and human intestinal epithelial cell line (8401)." (PMID 32732864, 2020). "In the present study, we tested the expression of EN2 in colorectal cancer and paired adjacent normal tissues, and then discovered that EN2 was upregulated in the CRC." (PMID 32732864, 2020). "In addition, circ_0000467 has been reported to regulate the development of colorectal cancer via the miR-382-5p/EN2 axis." (PMID 34346842, 2021). "Further, with the aim of exploring whether EN2 could be a potential prognostic factor for colorectal cancer, we performed Kaplan–Meier survival analysis on the basis of the EN2 expression levels of 165 colorectal cancer patients." (PMID 32732864, 2020). "EN2 was upregulated in colorectal cancer tissues compared with adjacent normal tissues." (PMID 32732864, 2020). "Combined, the results raised the conjecture that EN2 might be a transcription factor involving in the progression of colorectal cancer." (PMID 32732864, 2020). "However, the expression and the clinical significance of EN2 in colorectal cancer (CRC) are largely unknown." (PMID 32732864, 2020). "EN2 promotes the proliferation and invasion of colorectal cancer cells by regulating CCL20, thus promoting the progression of colorectal cancer." (PMID 36061185, 2022). "To identify critical engrailed genes that contribute to the colorectal cancer tumorigenesis, we analyzed the mRNA expression of EN1 and EN2 in GSE9348, in which EN2 was significantly upregulated in CRC." (PMID 32732864, 2020). "To investigate the molecular mechanism of EN2 in colorectal cancer, we explored the gene expression profiles change of CRC cells after knocking down EN2 through RNA sequencing." (PMID 32732864, 2020). "However, it remains unclear whether EN2 has any role in colorectal cancer." (PMID 32732864, 2020). "For example, EN2 plays a key role in promoting colorectal cancer progression primarily through the regulation of the expression of CCL20, which in turn promotes the proliferation and migration of colorectal cancer cells." (PMID 40889210, 2025).
autism spectrum disorder (7 papers, 2012 to 2024). A spectrum of developmental disorders that includes autism, and Asperger syndrome. "Previous genetic studies demonstrated association between the transcription factor ENGRAILED2 (EN2) and Autism Spectrum Disorder (ASD)." (PMID 24520327, 2014). "The relationship between the autistic spectrum disorder (ASD) and EN2 gene polymorphisms and mutations has been suggested since 1995." (PMID 30147646, 2018). "Actually, genetic alterations in the expression of EN2 have been related to different neurologic conditions and more particularly to autism spectrum disorder (ASD)." (PMID 30147646, 2018). "Genetic alterations in the expression of EN2 have been related to different neurologic conditions and more particularly to autism spectrum disorders (ASD)." (PMID 30147646, 2018). "Because of its roles in regulating cerebellar development and evidence of cerebellar pathology in autism spectrum disorder (ASD), we previously examined an ENGRAILED2 association and found evidence to support EN2 as a susceptibility gene, a finding replicated by several other investigators." (PMID 24507165, 2014). "Our findings provide new insight into the role of En2 in complex behaviors and suggest that disturbances in En2 signaling may contribute to neuropsychiatric disorders marked by social and cognitive deficits, including autism spectrum disorders." (PMID 22829897, 2012).
glioma (7 papers, 2019 to 2025). A benign or malignant brain and spinal cord tumor that arises from glial cells (astrocytes, oligodendrocytes, ependymal cells). "These lines of evidence indicate that FOSL1 and EN2, which are involved in our risk assessment model, have prognostic value in various tumors, including glioma." (PMID 36061185, 2022). "Taken together, all these findings indicate that EN2 expression is associated with a reduced glioma malignancy." (PMID 32158355, 2020). "EN2 expression is downregulated in human gliomas compared to adjacent brain tissues, which is negatively associated with glioma malignancy." (PMID 32158355, 2020). "EN2 is a suppressor of glioma tumorigenesis, which is downregulated in human gliomas and negatively associated with glioma malignancy." (PMID 32158355, 2020). "In this study, we identify that EN2 is reciprocally associated with glioma malignancy." (PMID 32158355, 2020). "The study identified eight co-downregulated miRNAs, three co-upregulated miRNAs, and seven genes associated with overall glioma survival, namely, KRAS, IFNB1, ALCAM, ERBB2, STAT3, FOSL1, and EN2." (PMID 36061185, 2022). "As risk factors for glioma, both FOSL1 and EN2 can be considered and further verified to be regulated and targeted by hsa-miR-33a." (PMID 36061185, 2022). "FOSL1 and EN2, which are target mRNAs of hsa-miR-33a, can be used to predict the prognosis of glioma based on the results of the bioinformatics analysis." (PMID 36061185, 2022). "EN2 is under-expressed in gliomas, and elevated EN2 expression restrains cell multiplication, enhances tumor sensitivity to temozolomide, and blocks tumor cell invasion by repressing MMP9 expression." (PMID 33685351, 2021). "Low expression of EN2 is observed in the subtype of glioma patients with poor survival, suggesting that EN2 expression is a conceivable biomarker for glioma prognosis." (PMID 32158355, 2020). "As a first step to identify the possible contributions of EN2 in gliomagenesis, we analyzed the EN2 gene expression profiles in tumor tissues compared with adjacent brain tissues in glioma patients from West China Hospital of Sichuan University." (PMID 32158355, 2020). "We conducted a Flag-tagged EN2 overexpressed U251 human glioma cells, in which EN2 is lowly expressed." (PMID 32158355, 2020). "Elevated EN2 expression inhibits cell proliferation, enhances glioma sensitivity to temozolomide and blocks cell invasion of glioma cells." (PMID 32158355, 2020). "Results from the CCK-8 assay indicated that EN2 overexpression reduced cell proliferation in glioma cells." (PMID 32158355, 2020). "In this study, we investigate the potential role of EN2 in human gliomas, and reveal a novel function of EN2 in regulating cell proliferation/apoptosis/invasion and participating in gliomagenesis." (PMID 32158355, 2020). "To reveal the molecular mechanism by which EN2 suppresses glioma cell migration/invasion, we examined and found that the protein level of MMP-9 was dramatically decreased by EN2 overexpression." (PMID 32158355, 2020). "By real-time PCR assay, we found that the mRNA level of EN2 was decreased in gliomas compared to adjacent brain tissues." (PMID 32158355, 2020). "Altogether, our results demonstrate that EN2 suppresses cell migration/invasion in glioma cells via MMP-9." (PMID 32158355, 2020). "To investigate the correlation of EN2 expression with clinical significance in gliomas, we performed Kaplan–Meier survival analysis and found that gliomas with higher EN2 expression carried a significantly better prognosis than those with lower EN2 expression." (PMID 32158355, 2020). "We identified that EN2 was downregulated in human gliomas compared with paired adjacent normal tissues and negatively associated with glioma malignancy." (PMID 32158355, 2020). "Elevated EN2 expression inhibits cell proliferation, enhances glioma sensitivity to temozolomide and inhibits migration/invasion of glioma cells." (PMID 32158355, 2020).
glioma (continued). "To investigate the biological functions of EN2 in glioma cells, we performed transcriptome sequencing (RNA-seq) in Flag-EN2 overexpressed cells with matched controls." (PMID 32158355, 2020). "Our data identify a novel function of EN2 in glioma suppression and provide potential therapeutic targets for glioma therapy." (PMID 32158355, 2020). "Elevated EN2 expression inhibits cell proliferation and enhances glioma sensitivity to temozolomide." (PMID 32158355, 2020). "Our study demonstrates that EN2 is a novel suppressor of glioma tumorigenesis by decreasing cell proliferation and invasion, as well as increasing cell apoptosis." (PMID 32158355, 2020). "Further examinations confirmed that EN2 expression was decreased in high-grade gliomas (WHO III and IV) in contrast to low-grade gliomas (WHO II), suggesting that EN2 expression is associated with lower glioma grade." (PMID 32158355, 2020). "Previous studies demonstrate that Engrailed-2 (EN2), a homeobox-containing transcription factor, is associated with tumorigenesis in a range of cancers heterogeneously, however, the profiles of EN2 expression and its potential functions in gliomas remain unclear." (PMID 32158355, 2020). "Here, using clinical samples combined with functional approaches, we demonstrate that EN2 is a novel suppressor of glioma tumorigenesis." (PMID 32158355, 2020). "Our data identify a novel function of EN2 in glioma suppression and provides potential targets for glioma therapy." (PMID 32158355, 2020). "All these results imply a novel function of EN2 in glioma suppression and provide potential targets for glioma therapy." (PMID 32158355, 2020). "To study the biological function of EN2 in glioma, we compared the cell viability and proliferation profiles between EN2 overexpressed and control cells using cell counting kit-8 (CCK8) assay, EdU incorporation assay and colony formation assay." (PMID 32158355, 2020). "It is worthwhile to note that the expression level of EN2, which improved G3/G4 classification performance, has been reported to alter glioma cell morphology." (PMID 31752658, 2019). "Therefore, the multifactorial Cox model developed by FOSL1 and EN2 can better predict glioma prognoses." (PMID 36061185, 2022). "To investigate whether FOSL1 and EN2 are independent prognostic factors, we divided all TCGA-glioma samples into high- and low-expression groups based on median gene expression values." (PMID 36061185, 2022). "In addition, it was found that EN2 expression levels are also correlated with the degree of malignancy of gliomas and promoted the malignant progression of glioma." (PMID 36061185, 2022). "Moreover, hsa-mir-33a co-targeting FOSL1 and EN2 has a good predictive value for glioma and skeletal muscle reduction." (PMID 36061185, 2022). "In this study, hsa-miR-33a was found to regulate FOSL1 and EN2 and affect the prognosis of gliomas." (PMID 36061185, 2022). "Interestingly, we noted that EN2 also plays a vital role in regulating cell invasion of glioma cells." (PMID 32158355, 2020). "Moreover, we confirmed the effect of EN2 on cell proliferation by EdU labeling assay and found that EdU positive cells were slightly decreased in EN2 overexpressed cells, suggesting that EN2 exert an inhibitory effect on glioma proliferation." (PMID 32158355, 2020). "Since the expression of EN2 is inversely correlated with glioma malignancy, we sought to determine whether EN2 functionally suppresses gliomagenesis." (PMID 32158355, 2020). "Mechanistically, EN2 inhibits glioma proliferation and invasion, and induces apoptosis." (PMID 32158355, 2020). "All these findings indicate that EN2 is a potential target for precision therapeutics of glioma." (PMID 32158355, 2020). "A typical feature of glioma is diffuse tumor invasion, and we sought to determine whether EN2 functionally suppresses glioma migration/invasion." (PMID 32158355, 2020). "Real-time PCR was used to identify the expression of EN2 in glioma tissues." (PMID 32158355, 2020).
glioma (continued). "To investigate whether EN2 regulates glioma tumorigenesis, we evaluate cell proliferation/apoptosis in U251 cells transfected by Flag-EN2." (PMID 32158355, 2020). "Finally, wound healing and transwell assays were carried out to investigate the role of EN2 on glioma cell invasion." (PMID 32158355, 2020). "This study obtained co-expressed differential miRNA genes by analyzing glioma and skeletal muscle miRNA datasets, followed by multifactorial Cox regression analysis and stepwise regression analysis to obtain a patient survival risk regression model, which included FOSL1 and EN2." (PMID 36061185, 2022). "FOSL1 and EN2 may affect the prognosis of gliomas independently." (PMID 36061185, 2022). "Moreover, EN2 blocks the invasion of glioma cells by inhibiting MMP9 expression." (PMID 32158355, 2020). "However, by applying rotenone and temozolomide to induce apoptosis, it’s found that EN2 overexpression dramatically increased cell apoptosis under pharmacological treatment, indicating that EN2 sensitizes glioma cells to cell death and synergizes with temozolomide." (PMID 32158355, 2020). "As for glioma, it remains unclear about EN2 expression pattern and potential functions." (PMID 32158355, 2020). "Indeed, we found that genes in cell proliferation/apoptosis were also controlled by EN2, suggesting that EN2 may participate in glioma tumorigenesis." (PMID 32158355, 2020). "Therefore, EN2 may be involved in the regulation of glioma growth and survival." (PMID 32158355, 2020). "In summary, miR-33a with differential expression in glioma and sarcopenia may affect the prognosis of glioma by targeting and regulating FOSL1 and EN2." (PMID 36061185, 2022). "With a multi-factor Cox regression model incorporating FOSL1 and EN2, we obtained ROC curves of 0.702 and 0.709, respectively, suggesting that glioma prognosis can be predicted by FOSL1 and EN2, which are differentially expressed in both cancer and aged muscle." (PMID 36061185, 2022). "However, these antibodies were not reliable to detect endogenous EN2 protein, because they cannot even recognize overexpressed EN2 in glioma cell lines (data not shown)." (PMID 32158355, 2020).
breast cancer (6 papers, 2008 to 2025). A primary or metastatic malignant neoplasm involving the breast. "Previous studies have demonstrated that the suppression of EN2 in breast cancer cell lines by siRNA against En-2 resulted in a significant decrease in their proliferation rate." (PMID 21566742, 2008). "Although En-2 was recently identified as a candidate oncogene in human breast cancer, very little is known about this regulatory gene relative to organogenesis and cancer." (PMID 21566742, 2008). "The mouse Engrailed-2 (En-2) gene, which is a homeobox-containing transcription factor was recently identified as a candidate oncogene in breast cancer." (PMID 21566742, 2008). "Previous reports confirmed that EN2 contributed to breast cancer as an oncogene." (PMID 33350453, 2021).
glioblastoma (5 papers, 2022 to 2025). The most malignant astrocytic tumor (WHO grade IV). "LEF1-AS1/miR-543/EN2 is a novel ceRNA network and is associated with the progression of glioblastoma." (PMID 37927791, 2023). "LEF1-AS1 is highly expressed in glioblastoma tissues, and in glioblastoma cells, this lncRNA can be targeted to miR-543, leading to the upregulation of EN2 expression." (PMID 37927791, 2023). "We found that hsa-mir-33a co-targeting FOSL1 and EN2 has a good predictive value for glioblastoma and skeletal muscle reduction." (PMID 36061185, 2022). "In glioblastoma, LEF1-AS1 has been demonstrated to act as a competing endogenous RNA (ceRNA) to sponge and downregulate miR-543, resulting in the upregulation of EN2 (engrailed homeobox 2) and increased tumor aggressiveness." (PMID 41511293, 2025). "LEF1-AS1 promotes the malignant behavior of glioblastoma cells, and LEF1-AS1 acts as a ceRNA of miR-543 and positively regulates the expression of EN2." (PMID 35563178, 2022).